TCAIM (T cell activation inhibitor, mitochondrial)
Description:
May regulate T-cell apoptosis.
Synonyms: TOAG-1; C3orf23; TOAG1; DKFZp313N0621
Tractability: Small molecule: a structure with a bound ligand is known. PROTAC: ubiquitination databases record sites on it; its protein half-life has been measured.
Gene: Protein-coding gene on chromosome 3 (44,338,119 to 44,409,451, forward strand). Ensembl gene ENSG00000179152.
Subcellular location: Mitochondrion
Gene Ontology:
Cellular component: mitochondrion
Genetic constraint (gnomAD): Loss-of-function variants: 33 observed, 58.93 expected, observed/expected ratio (o/e) 0.56, 90% interval 0.42 to 0.75. The upper end of that interval is the gene's LOEUF score, 0.75, which puts it in group 3 of 6, group 1 being the genes least tolerant of losing a copy. Missense variants: 456 observed, 587.14 expected, observed/expected ratio (o/e) 0.78, 90% interval 0.72 to 0.84. Synonymous variants: 166 observed, 196.58 expected, observed/expected ratio (o/e) 0.84, 90% interval 0.74 to 0.96.
Homologues: Orthologues: chimpanzee TCAIM (99% identical), macaque TCAIM (99% identical), dog TCAIM (94% identical), rabbit TCAIM (92% identical), pig TCAIM (90% identical), rat Tcaim (84% identical), mouse Tcaim (83% identical), guinea pig TCAIM (82% identical), tropical clawed frog tcaim (61% identical), zebrafish tcaim (55% identical), Drosophila melanogaster CG13295 (22% identical), Drosophila melanogaster CG2854 (18% identical), and 1 more.
Diseases named in the same sentence as TCAIM in open-access papers:
TCAIM is named in the same sentence as 1 disease in open-access papers, as found by Europe PMC text mining. Sharing a sentence is not in itself a finding about the gene and the disease.
TCAIM shares sentences with these, for which no sentence is quoted: kidney transplant (1 paper).